TEAD4 (TEA domain transcription factor 4)
Diseases named in the same sentence as TEAD4 in open-access papers (continued):
Sharing a sentence is not in itself a finding about the gene and the disease.
gastric adenocarcinoma (3 papers, 2018 to 2025). "It is reported that TEAD4 upregulated CDC25B in gastric adenocarcinoma, driving cell aggressiveness and inhibiting sensitivity to cisplatin therapy through cell adhesion." (PMID 40404896, 2025). "In DErrico’s and Cho’s dataset, higher expression levels of TEAD4 were found in gastric intestinal type adenocarcinoma (fold change = 6.960) and gastric adenocarcinoma (fold change = 2.015)." (PMID 35739490, 2022). "By using the GEPIA dataset, we further compared the expression of TEADs in stomach adenocarcinoma with normal samples, and consistent with Cho’s results, the expression level of TEAD4 was about 2 folds in tumor than normal samples." (PMID 35739490, 2022). "TEADs were altered about 14% (67 samples out of 478 samples) in patients with stomach adenocarcinoma, and the proportion of amplification in genetic alterations was 30% for TEAD3 and 36% for TEAD4." (PMID 35739490, 2022).
mesothelioma (3 papers, 2022 to 2025). A usually malignant and aggressive neoplasm of the mesothelium which is often associated with exposure to asbestos. "Previous studies have shown that CA3, a novel YAP1/TEAD4 transcriptional activity inhibitor, targets cancer stem cells in esophageal adenocarcinoma and mesothelioma." (PMID 36180487, 2022). "Therefore, despite the absence of YAP track in the Cistrome DB of A549 cells, we assume that YAP binds PTEN promoter since a YAP peak overlapping with TEAD4, YY1 and MYC is present in the mesothelioma cell line H2052." (PMID 39455556, 2024).
sarcoma (3 papers, 2016 to 2021). A usually aggressive malignant neoplasm of the soft tissue or bone. "The TEAD family of transcription factors (TEAD1, TEAD2, TEAD3 and TEAD4) are the terminal nuclear effectors of the Hippo pathway, which is usually overactivated in sarcoma." (PMID 33993634, 2021).
triple-negative breast carcinoma (3 papers, 2015 to 2021). An invasive breast carcinoma which is negative for expression of estrogen receptor (ER), progesterone receptor (PR), and human epidermal growth factor receptor 2 (HER2). "As a target gene of the TEAD4 transcription factor, GTSE1, which transcriptional regulation related to the YAP and TAZ coactivator, plays an important role in triple-negative breast cancer." (PMID 31781484, 2019).
carcinoma in situ (2 papers, 2018 to 2022). "Positive TEAD4 staining was commonly observed in carcinoma (87.5%, 7/8), but much less in samples with healthy mucosa (12.5%, 1/8), hyperplasia (25.0%, 2/8) or dysplasia/carcinoma in situ (37.5%, 3/8)." (PMID 30459528, 2018). "To assess the role of TEAD4 in BLCA, we interrogated a BLCA TMA to determine its expression in this cancer and the association of its expression with patient survival, tumor grade (Low grade, High grade), tumor stage (stage I-IV), T stage (carcinoma in situ [Tis], Ta, T1–T4) and N stage (N0, N1)." (PMID 35581606, 2022). "Immunohistochemical staining in these samples indicated significant strong nuclear staining of TEAD4 in carcinoma in situ and invasive carcinoma, while negative or low staining in normal tongue mucosa and epithelial with hyperplasia." (PMID 30459528, 2018).
cervical cancer (2 papers, 2017 to 2020). A primary or metastatic malignant neoplasm involving the cervix. "The following genes ENO1, FOSB, PA2G4, SOX9, and TEAD4 were highly expressed in cervical cancer in comparison to normal cervix (p < 0.001), while FOXO4 and MNT were significantly lower in cervical cancer (p < 0.001)." (PMID 28670312, 2017). "We found that HPV E6/E7-related master regulators (ENO1, FOSB, PA2G4, SOX9, TEAD4, FOXO4, and MNT) were significantly differently expressed (p < 0.001) in the cervical cancer TCGA samples (n = 306) than in normal cervix (n = 11) tissue." (PMID 28670312, 2017).
colorectal adenoma (2 papers, 2021). An adenoma that arises from the colon or rectum. "A study has reported that the expression of TEAD4 in colorectal adenomas was positively associated with YAP1 expression and regulated its expression through transcription activation." (PMID 33517828, 2021). "We further note that immunostaining for the TEAD4 protein in the Human Protein Atlas database reveals a gradient of expression along the crypt‐villus axis in the human small intestine and colon, and is uniformly induced in human colorectal adenomas, similar to Sox9." (PMID 33950519, 2021).
cutaneous melanoma (2 papers, 2018 to 2022). A primary melanoma arising from atypical melanocytes in the skin. "We have previously identified genetic variants of Hippo pathway genes (YAP1 rs11225163, TEAD1 rs7944031 and TEAD4 rs1990330) and revealed that Hippo effector TAZ significantly associated with unfavorable survival in cutaneous melanoma and primary OSCC." (PMID 30459528, 2018). "For example, Hippo pathway genes YAP1, TEAD1, and TEAD4 may jointly modulate the survival of cutaneous melanoma patients." (PMID 35739490, 2022).
endometrial cancer (2 papers, 2020 to 2022). Primary or metastatic malignant neoplasm involving the endometrium (mucous membrane that lines the endometrial cavity). "The transcriptional complex of TEAD4 and AP-1 controls cell migration and invasion by regulating its downstream targets such as CDH2 (Cadherin 2) and MACF1 (Microtubule Actin Crosslinking Factor 1) in endometrial cancer and other cancers." (PMID 35602596, 2022).
hepatoblastoma (2 papers, 2019 to 2024). Hepatoblastoma (HB) is a malignant hepatic tumor and is the most common pediatric liver cancer. "Furthermore, the increased mRNA expression of TEAD4 in human hepatoblastoma tissues suggests that TEAD-mediated transcriptional activity may be crucial for YAP-β-catenin-induced development of hepatoblastoma." (PMID 31511432, 2019).
leiomyosarcoma (2 papers, 2021 to 2023). An uncommon, aggressive malignant smooth muscle neoplasm, usually occurring in post-menopausal women. "This study aimed to investigate the expression profile and functional regulation of NT5DC2 and its potential interplay with TEAD4 in leiomyosarcoma (LMS)." (PMID 33993634, 2021). "The overexpression of TEAD4 was associated with poor survival, suggesting that NT5DC2 plays an important role in the development of leiomyosarcomas and may serve as a potential therapeutic target." (PMID 37576396, 2023).
liver fibrosis (2 papers, 2023 to 2025). "Upregulated CD47, triggered by the YAP and TEAD4 genes, leads to the heightened activation of HSCs, resulting in liver fibrosis." (PMID 40786064, 2025). "Therefore, silencing or knocking down the CD47/YAP/TEAD4 pathway can inhibit the fibrotic gene expression, thereby attenuating liver fibrosis pathology." (PMID 40786064, 2025). "In addition, novel pathways pertaining to liver fibrosis, such as the RSPO3-LGR4/5-β-catenin cascade, the CD47/YAP/TEAD4 signalling axis, and HAb18G/CD147, are briefly elaborated in the context of therapeutic approaches for arresting HSC activation." (PMID 40786064, 2025). "Moreover, pharmacological intervention in the communication halting between YAP and TEAD4 will further potentially reduce the chances of HSC activation and liver fibrosis." (PMID 40786064, 2025). "This indicates that the high expression of CIT can mediate the fibrosis progression of NASH, thereby leading to the occurrence and development of HCC, and TEAD4 and SOCS2 may affect HCC through pathways other than liver fibrosis." (PMID 38102321, 2023).
non-small cell lung carcinoma (2 papers, 2016 to 2024). A group of at least three distinct histological types of lung cancer, including non-small cell squamous cell carcinoma, adenocarcinoma, and large cell carcinoma. "Next, we surgically collected paired non-small cell lung cancer (NSCLC) samples and adjacent normal tissues from seven patients, and measured the relative levels of two TEAD4 isoforms." (PMID 27291620, 2016).
oral squamous cell carcinoma (2 papers, 2018 to 2019). "Similarly, it was reported that Yap1 formed complex with TEAD4 in the nuclei regulating the transcriptions of G1 arrest-related genes, such as CCND1, CCNE, CDK2, CDK4, and CDK6, in human oral squamous cell carcinomas." (PMID 31455378, 2019).
psoriasis (2 papers, 2024 to 2025). An autoimmune condition characterized by red, well-delineated plaques with silvery scales that are usually on the extensor surfaces and scalp. "TEA domain family member 4 (TEAD4), as a transcription factor, is overexpressed in keratinocytes of psoriasis." (PMID 39737188, 2024). "In keratinocytes, TEAD4 knockdown reduced the expression of CXCL1, CXCL5, and CXCL8, critical inflammatory mediators involved in the pathogenesis of psoriasis." (PMID 41550920, 2025). "Specifically, analysis of lesional and non-lesional skin biopsies from patients with psoriasis revealed that TEAD4, a key transcription factor of YAP, is highly expressed in psoriatic lesions." (PMID 41550920, 2025).
thymic carcinoma (2 papers, 2023 to 2026). Thymic carcinoma (TC) is a type of thymic epithelial neoplasm characterized by a high malignant potential. "TAZ and TEAD4 displayed both cytoplasmic and nuclear immunoreactivity in almost equal frequency, with their cytoplasmic H-score being strongly associated with more aggressive high-grade tumors (type B3, thymic carcinoma) and more advanced pathological stages." (PMID 37509515, 2023).
thymoma (2 papers, 2025 to 2026). A neoplasm arising from the epithelial cells of the thymus. "On the other hand, both type A/AB thymomas and TCs displayed higher levels of nuclear TEAD4 expression compared to thymomas type B1, B2, and B3 (Kruskal–Wallis ANOVA, p = 0.005)." (PMID 40649713, 2025). "Cytoplasmic TEAD4 expression was higher in TCs compared to thymomas (Mann–Whitney U test, p = 0.002) and in advanced tumor stage (Mann–Whitney U test, I/II versus III/IV, p < 0.001)." (PMID 40649713, 2025).
thyroid cancer (2 papers, 2022 to 2025). "Overexpressed TEAD4 suppresses thyroid cancer progression and metastasis via maintaining an appropriate Wnt signaling by upregulating Wnt3a." (PMID 35602596, 2022).
age-related macular degeneration (1 paper, 2012). Age-related loss of vision in the central portion of the retina (macula), secondary to retinal degeneration. "In addition we demonstrate the presence of TEAD4 protein in choroidal neovascular membrane in human age-related macular degeneration, suggesting a role in human disease." (PMID 22761647, 2012).
Alcoholism (1 paper, 2018). "Among them, AD-specific module AD_M1 is regulated by SP1, TEAD4, PCBP1 with targets in the pathway of regulation of actin cytoskeleton, cAMP signaling pathway, PI3K-Akt signaling pathway, metabolic pathways, Alcoholism, and PPAR signalling pathway." (PMID 30598117, 2018).
Burkitt lymphoma (1 paper, 2021). A rare form of malignant mature B-cell non-Hodgkin lymphoma. "In support of our results here, results presented in the Human Protein Atlas database indicate that RNA transcripts of YAP, TAZ, and the four TEAD family members (TEAD1, TEAD2, TEAD3, and TEAD4) are not detected in the EBV-infected Burkitt lymphoma cell line, Daudi." (PMID 34339458, 2021).
cervical tumor (1 paper, 2017). "According to the available data in the Human Protein Atlas, most of tested cervical tumor samples were positive for protein expression of EGR3, NR4A2, SOX9, PA2G4, ENO1, and TEAD4." (PMID 28670312, 2017).
Cognitive impairment (1 paper, 2022). Abnormal cognition is characterized by deficits in thinking, reasoning, or remembering. "Leveraging an LPA-derived phenotype and genetics data, we identified two genome-wide significant loci in our genome-wide association analysis for LPAx (a data-derived cognitive impairment outcome): TEAD4 (rs11829294, p value = 2.40e-8) and STX18 (rs79453226, p value = 1.91e-8)." (PMID 35240980, 2022). "Along with the evidence that variant rs12322215 is linked to the promoter region of PRMT8, we conclude that PRMT8 is another biologically plausible gene regulated by eQTL at the TEAD4 locus that could have potential effects on cognitive impairment among preterm children." (PMID 35240980, 2022).
colorectal adenocarcinoma (1 paper, 2021). The most common type of colorectal carcinoma. "In colorectal adenocarcinoma (COAD and READ), TEAD4 has been shown to be a biomarker and tumorigenic promoter and has been identified as a possible target for therapies." (PMID 33778495, 2021).
coronary artery disease (1 paper, 2020). "Our results showed that the motif of transcriptional enhancer factor TEF-3 (TEAD4) was significantly enriched in 5hmC gain regions (P ≤ 0.01), which was a transcriptional factor regulating gene expression in muscle and to control cell proliferation and associated with coronary artery disease risk." (PMID 31964422, 2020).
idiopathic pulmonary fibrosis (1 paper, 2024). Idiopathic pulmonary fibrosis (IPF) is a nonneoplastic pulmonary disease that is characterized by the formation of scar tissue within the lungs in the absence of any known cause. "Interestingly, we also have identified significant DEG-enrichments of target gene sets for five TFs, TCF12, ZEB1, NR3C1, TEAD4 and JUN, which were previously reported to be the regulators in idiopathic pulmonary fibrosis." (PMID 39103936, 2024).
invasive carcinoma (1 paper, 2018). A carcinoma that is not confined to the epithelium, and has spread to the surrounding stroma. "Moreover, results from 4NQO-induced HNSCC model showed that TEAD4 expression increased along with disease initiation and progression from hyperplasia to invasive carcinoma." (PMID 30459528, 2018).
ischemia (1 paper, 2016). A hypoperfusion of the BLOOD through an organ or tissue caused by a PATHOLOGIC CONSTRICTION or obstruction of its BLOOD VESSELS, or an absence of BLOOD CIRCULATION. "The TEA domain family member 4, Tead4 has been demonstrated to induce hypertrophy of rat cardiomyocytes through α1-adrenergic receptor stimulation and to up-regulate Hif1α, thus stimulating vascular development and heart recovery after ischemia." (PMID 26979619, 2016).
laryngeal carcinoma (1 paper, 2022). Carcinoma that arises from the laryngeal epithelium. "High expression of YAP1, TEAD4, and TP73 was significantly associated with high grade, advanced stage, supraglottic location of tumors, nodal metastases, and recurrence of human laryngeal cancer." (PMID 36479120, 2022).
muscle atrophy (1 paper, 2025). The loss of muscle tissue due to inactivity or disease. "TEAD4, FOS and MYC are essential for embryonic skeletal muscle development, activation of these regulons in RCT implicates the activation of an early developmental program in the pathogenesis of muscle atrophy." (PMID 39435630, 2025).
pertussis (1 paper, 2022). A contagious bacterial respiratory infection caused by Bordetella pertussis. "The downregulated genes in the TEAD4-high group belonged to pathways of pertussis, cytokine–cytokine receptor interaction, phagosome, etc., and were involved in bioprocesses of the humoral immune response, respiratory gaseous exchange by the respiratory system, and metabolic process, etc.." (PMID 35600867, 2022).
placental tumor (1 paper, 2024). "For example, GATA3 and AP2 gamma (TFAP2C), two TFs that were recently reported to cooperate with TEAD4 and VGLL1 to differentiate pluripotent stem cells into trophoblast stem cells, were also identified from our ChIP-seq analysis of breast and placental tumor cells." (PMID 38912065, 2024).
renal carcinoma (1 paper, 2024). A carcinoma arising from the epithelium of the renal parenchyma or the renal pelvis. "TEAD4 depletion, indeed, attenuated proliferation and migration in renal cancer cell lines and xenograft growth in vivo, highlighting an important role of TEAD4 in RCC progression." (PMID 39123485, 2024).
Renal cyst (1 paper, 2020). A fluid filled sac in the kidney. "Furthermore, we demonstrated that SNX9 interacted directly with YAP and promoted LATS1-mediated YAP phosphorylation, resulting in the cytoplasmic retention of YAP and the transcriptional inactivation of the YAP/TEAD4 complex, which, consequently, retards renal cyst development." (PMID 32974348, 2020).
retinoblastoma (1 paper, 2024). A malignant tumor that originates in the nuclear layer of the retina. "YAP, YAP5SA, and TEAD4(DBD)-VP64, but not controls, also induced UNC5B in WERI-RB1 retinoblastoma cells." (PMID 39172021, 2024).
Sepsis (1 paper, 2022). Sepsis is defined as life-threatening organ dysfunction caused by a dysregulated host response to infection. "Tead4 levels are high in the skeletal muscle tissue in mouse model of acute sepsis." (PMID 35812340, 2022).
testicular germ cell tumor (1 paper, 2015). A germ cell tumor arising from the testis. "Similarly, amplification and overexpression of TEAD4 were in serous fallopian tube carcinoma and testicular germ cell tumors, and TEAD4 alone promoted anchorage-independent growth in MCF10A cells." (PMID 25970772, 2015).
ulcerative colitis (1 paper, 2025). An inflammatory bowel disease involving the mucosal surface of the large intestine and rectum. "Gancao Xiexin decoction attenuates ferroptosis in ulcerative colitis (UC) via the TEA domain transcription factor 4 (TEAD4)/ACSL4 signaling pathway." (PMID 41288931, 2025).